CXCR2 (C-X-C motif chemokine receptor 2)
Diseases named in the same sentence as CXCR2 in open-access papers (continued):
Sharing a sentence is not in itself a finding about the gene and the disease.
hyperlipidemia (2 papers, 2021 to 2025). "Therefore, the current study suggests that genes involved in these directly related hyperlipidemia pathways such as RAF1, GRK3 and CXCR2 were significant feature genes associated with hyperlipidemia." (PMID 41446394, 2025). "Pharmacology or antibody-mediated antagonism of neutrophil depletion by CXCR2 or an anti-Ly6G antibody can restore neural function and reverse brain injury caused by hyperlipidemia, thus revealing the functional significance of neutrophils in the pathogenesis of ischemic brain injury." (PMID 34335600, 2021). "Thus, it can be speculated that CXCR2 is closely associated with the pathogenesis of hyperlipidemia and as a biomarker of hyperlipidemia in further research." (PMID 41446394, 2025). "After hyperlipidemia and ischemia, brain neutrophil infiltration and peripheral neutrophil increase, and the use of CXCR2 antagonist reduces neutrophil infiltration." (PMID 34335600, 2021). "At the same time, the feature genes, including RAF1, GRK3 and CXCR2 may be potential genetic biomarkers of hyperlipidemia." (PMID 41446394, 2025). "The hub genes such as RAF1, GRK3 and CXCR2, might be potential genetic biomarkers of hyperlipidemia." (PMID 41446394, 2025).
hyperreactivity (2 papers, 2022). "The overproduction of mucus and the development of airway hyperreactivity in mice were shown to be directly associated with the expression and activation of CXCR2 (an IL-8 receptor homolog), which is a receptor associated with neutrophilia." (PMID 36294363, 2022). "Similar experiments demonstrated that neutralization of CXCR2, the receptor for the chemokines CXCL1, CXCL2, granulocyte chemoattract protein 2, and LPS-induced CXC chemokine, prevents RSV-induced airway hyperreactivity but does not alter viral clearance." (PMID 35062301, 2022).
hypertensive retinopathy (2 papers, 2022 to 2025). Retinopathy due to hypertension. "We evaluated the expression levels of a series of chemokines (CXCL1, CXCL2, CXCL3 and CXCL5) and their receptor CXCR2 in Ang II-treated retinas to investigate the role of chemokines and their receptors in hypertensive retinopathy." (PMID 35981418, 2022). "The contribution of neuronal and endothelial CXCR2 to hypertensive retinopathy remains to be explored." (PMID 35981418, 2022).
intracerebral haemorrhage (2 papers, 2023 to 2025). "The relevant raw data can be found in: WU, JIAWEI; ZHAO, XUDONG (2025), “Vinorine targets the CXCR2‐JAK‐STAT axis to regulate microglial polarisation and alleviate secondary damage in Intracerebral hemorrhage”, Mendeley Data, V1, doi: 10.17632/r84sbmwsjk." (PMID 40994248, 2025).
invasive breast carcinoma (2 papers, 2020 to 2023). A carcinoma that infiltrates the breast parenchyma. "Variable density of CXCR2-positive cells was observed in invasive breast cancer samples." (PMID 32727083, 2020).
ischemia reperfusion injury (2 papers, 2022 to 2024). Adverse functional, metabolic, or structural changes in ischemic tissues resulting from the restoration of blood flow to the tissue (reperfusion), including swelling; hemorrhage; necrosis; and damage from free radicals. "In unilateral ischemia-reperfusion injury (UIRI) mice, treatment with interlukin-8 (IL-8), the ligand of CXCR2, further aggravated β-catenin activation, mitochondrial dysfunction, tubular cell senescence and renal fibrosis, whereas knockdown of p16INK4A inhibited IL-8-induced these effects." (PMID 35592244, 2022).
laryngeal carcinoma (2 papers, 2019). Carcinoma that arises from the laryngeal epithelium. "Inhibition of IL-8 binding to CXCR2 partially restored the effect of pepsin on laryngeal cancer cells." (PMID 30936780, 2019).
leukocytosis (2 papers, 2023 to 2024). "Furthermore, inhibition of CXCR-2 in tumors with leukocytosis, including CC, has been suggested to be a promising therapeutic target." (PMID 37626777, 2023).
Listeria monocytogenes infection (2 papers, 2018 to 2020). "We therefore examined if enhanced neutrophil responses mediate the decreased susceptibility of Sdc1-/- mice to listeriosis by testing the effects of neutralizing antibodies against CXCR2 or C5aR." (PMID 32453780, 2020). "In a model of Listeria monocytogenes infection, IFNγ downregulates expression of CXCR2 (the only receptor for CXCL2 in mice) on neutrophils, thereby curtailing their recruitment to the site of inflammation." (PMID 30012158, 2018).
liver cirrhosis (2 papers, 2011 to 2017). "Then, considering the key role of the HSC cells in liver cirrhosis and hepatocarcinogenesis, the CXCR1 and CXCR2 axes were studied in MSC migration to LX-2 CM." (PMID 29113298, 2017). "Furthermore, these findings paralleled the intrahepatic expression patterns of up-regulated CXCR1, but not CXCR2, in patients with liver cirrhosis." (PMID 21731723, 2011).
malaria (2 papers, 2012 to 2020). Malaria is a serious and sometimes fatal disease caused by a parasite that commonly infects a certain type of mosquito which feeds on humans. "The poor migration of neutrophils from malaria patients was associated with decreased expression of the chemokine receptor CXCR2, as indicated by qPCR and FACS." (PMID 22745844, 2012). "The observed high levels of circulatory IL-8 may mediate desensitization and/or down-regulation of CXCR2 in acutely infected malaria patients." (PMID 22745844, 2012). "Interestingly, neutrophils from the malaria patients expressed high levels of GRK2, low levels of CXCR2, and displayed impaired chemotaxis towards IL-8 (CXCL8)." (PMID 22745844, 2012). "Thus, decreased expression of CXCR2 and CD88 on neutrophils from malaria patients may be a consequence of an enhanced expression of GRK2." (PMID 22745844, 2012).
malignant mesothelioma (2 papers, 2017 to 2023). A malignant neoplasm of the pleura or peritoneum, arising from mesothelial cells. "In contrast, in the malignant mesothelioma cell line panel, CCL2 expression was downregulated compared to the marked increase in CXCR2-dependent chemokines, IL-1α, and VEGF-A underscoring the critical role played by cell type in the context of arginine deprivation therapy." (PMID 37010783, 2023).
MALT lymphoma (2 papers, 2015). An indolent, extranodal type of non-Hodgkin lymphoma composed of small B-lymphocytes (centrocyte-like cells). "As for the 17 GI-FL, 16 nodal FL, and 10 GI-MALT lymphoma cases, interleukin-8 receptor β (IL-8RB) (CXCR2) protein expression was assessed using immunohistochemical analysis." (PMID 26674732, 2015). "In comparing gastric to extragastric MALT lymphomas, the upregulation of CXCR1 and CXCR2 accompanied by downregulation of CCR8 and CX3CR1 and loss of XCR1 expression in extragastric MALT lymphomas appear to be key determinants for the site of origin of MALT lymphomagenesis." (PMID 25922601, 2015).
mesothelioma (2 papers, 2017 to 2021). A usually malignant and aggressive neoplasm of the mesothelium which is often associated with exposure to asbestos. "Although we observed CXCR2 expression on 30% of M-MDSC, anti-CXCR2 therapy failed to reduce the recruitment of M-MDSC in mesothelioma." (PMID 33578808, 2021).
metastatic carcinoma (2 papers, 2012 to 2019). A carcinoma which has spread from the original site of growth to another anatomic site. "Nineteen patients displayed abundant expression of both hPTTG1 and CXCR2 in both primary and metastatic carcinomas." (PMID 22789011, 2012). "The number of specimens weakly expressing both hPTTG1 and CXCR2 increased from 2% (one of 50) in primary IDCs to 26% (13 of 50) in metastatic carcinomas." (PMID 22789011, 2012). "According to an IHC analysis of hPTTG1 and CXCR2 expression, we classified these primary IDCs and metastatic carcinomas into the following four groups: hPTTG1 (2+,3+)/CXCR2 (2+,3+); hPTTG1 (2+,3+)/CXCR2 (1+,0+); hPTTG1 (1+,0+)/CXCR2(2+,3+); and hPTTG1 (1+,0+)/CXCR2 (1+,0+)." (PMID 22789011, 2012). "Notably, eight patients demonstrated abundant expression of both hPTTG1 and CXCR2 in primary IDCs but lost the expression of both hPTTG1 and CXCR2 in metastatic carcinomas." (PMID 22789011, 2012). "Therefore, the hPTTG1-induced SASP may benefit the metastasis of neighboring nonsenescent cancer cells, which would explain why the metastatic nonsenescent cancer cells displayed low expression levels of both hPTTG1 and CXCR2 in metastatic carcinomas (for example, Patient 1)." (PMID 22789011, 2012).
mucocutaneous leishmaniasis (2 papers, 2011 to 2024). The most common form of leishmaniasis that is transmitted through the bite of female phlebotomine sand flies or after exposure to leishmania parasites. "Variants at CXCR1 and CXCR2 have been associated with susceptibility to cutaneous and mucocutaneous leishmaniasis in Brazil." (PMID 22171941, 2011).
Nephroblastoma (2 papers, 2013 to 2022). An embryonal neoplasm characterized by the presence of epithelial, mesenchymal, and blastema components. "Nephroblastoma is sensitive to CXCR2 antagonist-induced apoptosis." (PMID 35837284, 2022). "Although SB225002 was first developed for the treatment of inflammatory diseases, recent studies suggest that retrovirus infections, Wilms’ tumor and Alzheimer’s disease may be potential therapeutic indications for CXCR2 antagonist." (PMID 23359652, 2013). "Thus, active CXCL7/CXCR2 signaling maintains nephroblastoma survival." (PMID 35837284, 2022). "The CXCL7/CXCR2 axis could be a new target for nephroblastoma therapy." (PMID 35837284, 2022). "Recent evidence indicates that CXCR2 signaling is crucial for cancer progression, and its antagonist SB225002 induces apoptosis in Wilms’ tumor cells." (PMID 23359652, 2013).
neuroendocrine tumor (2 papers, 2021 to 2024). "CXCR2 is overexpressed predominantly in neuroendocrine tumor (NE) cells, which produce CXCL8; whereas, CXCR1 expression appears to be restricted to non-NE tumor cells." (PMID 39766038, 2024).
non-alcoholic steatohepatitis (2 papers, 2021 to 2024). "LCN are members of a family of evolutionarily conserved genes and participate in non‐alcoholic steatohepatitis by promoting neutrophil‐macrophage crosstalk via the induction of CXCR2 and influence macrophage polarization to promote liver regeneration." (PMID 38710666, 2024). "CXCR2 mediates the recruitment of various leukocytes, e.g., granulocytes, NK cells, T cells and monocytes to the tissue able to modulate the fibrogenic response in non-alcoholic steatohepatitis." (PMID 33525493, 2021).
oral mucositis (2 papers, 2018 to 2025). Inflammation of the mucous membranes of any of the structures in the mouth. "Altogether, these findings indicate that CXCR2 overexpression in MSCs accelerates ulcer healing, providing new insights into cell-based therapy for radiation/chemical-induced oral mucositis." (PMID 29445104, 2018). "In radiation—or chemically induced oral mucositis mouse studies, MSC that overexpress CXCR2 can enhance their targeting to the site of inflammation, with stronger cell survival, and thus accelerate ulcer healing." (PMID 40984643, 2025). "By systematically evaluating the expression patterns of chemokines in radiation/chemical-induced oral mucositis, we found that CXCL2 was highly expressed, whereas cultured MSCs negligibly express the CXCL2 receptor CXCR2." (PMID 29445104, 2018).
pancreatitis (2 papers, 2015 to 2020). Inflammation of the pancreas. "Importantly, pharmacological inhibition of CXCR2 in wild‐type mice replicated the protection seen in Cxcr2−/− mice in acute and chronic models of pancreatitis." (PMID 25950520, 2015). "CXCR2 may therefore be a viable therapeutic target in the treatment of pancreatitis." (PMID 25950520, 2015). "Importantly, Pdx1‐Cre, Cxcr2fl/fl mice, in which Cxcr2 is deleted from pancreatic epithelial cells, were not protected from pancreatitis." (PMID 25950520, 2015).
peritonitis (2 papers, 2021 to 2022). Inflammation of the peritoneum (tissue that lines the abdominal wall and covers most of the organs in the abdomen). "To evaluate the role of CXCR2 in the mobilization of donor neutrophils in response to inflammatory stimuli, we analyzed the cellular composition of peripheral blood before and after mice received intraperitoneal thioglycollate to induce a sterile peritonitis." (PMID 35127689, 2022).
pituitary adenomas (2 papers, 2017 to 2022). "In addition, CXCR2 has been identified as a fundamental mediator in tumorigenesis not only in malignant tumors but also in pituitary adenomas." (PMID 29081734, 2017).
polyarthritis (2 papers, 2011 to 2020). "Another CXCR2 inhibitor, DF2162, significantly attenuated adjuvant-induced polyarthritis in rats." (PMID 33087182, 2020).
polyp (2 papers, 2024). A usually exophytic mass attached to the underlying tissue by a broad base or a thin stalk. "CD44, CXCR2 and c-myc levels showed around a 1.30- to 1.80-fold increase in polyp subjects when compared to normal subjects, whereas the CXCR2 and c-myc levels were around 0.5- to 0.7-fold lower in polyp subjects when compared to those in CRC subjects." (PMID 38891062, 2024). "We further determined the expression levels of CD44, IL8, CXCR2 and c-myc in an independent validation study consisting of rectal swab specimens from 60 normal subjects, 45 CRC subjects and 68 polyp patients." (PMID 38891062, 2024).
preeclampsia (2 papers, 2019 to 2020). Preeclampsia is a hypertensive disorder of pregnancy that is characterized by new-onset hypertension with proteinuria presenting after 20 weeks of gestation, and depending on mild or severe forms may initially present with severe headache, visual disturbances, and hyperreflexia. "The role of single nucleotide polymorphisms (SNPs) of CXCR2 gene in the pathogenesis of preeclampsia remains largely unexplored." (PMID 30714340, 2019). "Our study aimed to analyze the influence of CXCR2 polymorphisms on the predisposition of preeclampsia." (PMID 30714340, 2019). "Our study suggests a genetic association between rs1126579 polymorphism in CXCR2 gene and increased risk of preeclampsia." (PMID 30714340, 2019). "Whether the rs1126579 variation has a possible link with potential changes in the function of CXCR2‐associated pathways in patients with preeclampsia remains to be explored in the future." (PMID 30714340, 2019). "However, little is known about the possible impact of CXCR2 gene polymorphism on the development of preeclampsia." (PMID 30714340, 2019). "Thus, we aimed to investigate the association between polymorphisms of CXCR2 gene and preeclampsia in Han Chinese women." (PMID 30714340, 2019). "However, the role of CXCR2 gene polymorphism in the development of preeclampsia remains unexplored." (PMID 30714340, 2019). "Some reports suggest that Cxcr2 might contribute to the development of preeclampsia and in the control, pregnancy tolerance through neutrophils." (PMID 32041848, 2020). "Previous study has demonstrated that the decreased CXCR2 in preeclamptic placentas may contribute to the development of preeclampsia." (PMID 30714340, 2019). "Thus, further investigations are warranted to complement our results and illuminate the relationship between CXCR2 gene variation and the development of preeclampsia." (PMID 30714340, 2019). "Furthermore, a recent study has demonstrated that the decreased CXCR2 in preeclamptic placentas may contribute to the development of preeclampsia through impairing trophoblast invasion by down‐regulating MMP‐2 and MMP‐9 via the Akt signaling pathway." (PMID 30714340, 2019). "CXCR2, the receptor of the CXC chemokines, is identified to contribute to the pathogenesis of preeclampsia." (PMID 30714340, 2019).
Primary Sjögren’s Syndrome (2 papers, 2021 to 2024). "Furthermore, the CXCR2 expression level in MSG and plasma was significantly associated with the diffusing capacity of the lungs for carbon monoxide, erythrocyte sedimentation rate, and EULAR Sjögren’s Syndrome disease Activity Index in ILD-pSS." (PMID 34055876, 2021). "Our data were in agreement with the findings of Lisi and co-investigators, and they demonstrated that GRO-α/CXCR2 system and ADAM17 correlated expression in sjögren’s syndrome." (PMID 39305454, 2024).
prostate (2 papers, 2019 to 2024). "A third factor that could account for the differential effect of CXCR1 versus CXCR2 expression in prostate tumorigenesis could be the expression of chemokines in the tumor microenvironment (TME)." (PMID 39766038, 2024). "Since CXCR2 expression was shown to promote PCa growth the data likely indicate that CXCR1 and CXCR2 play opposing roles in prostate tumorigenesis." (PMID 39766038, 2024). "In contrast to CXCR2, CXCR1 expression inhibited PSA expression suggesting that the two receptors may couple to distinct pathways to modulate prostate tumorigenesis." (PMID 39766038, 2024).
prostate adenocarcinoma (2 papers, 2019 to 2021). "For example, active YAP in murine prostate adenocarcinoma promotes CXCL5 (C-X-C motif chemokine ligand 5) secretion, which attracts CXCR2 (C-X-C motif chemokine receptor 2)-expressing myeloid derived suppressor cells (MDSC) to suppress the immune responses." (PMID 31052239, 2019). "Despite IL-8 and CXCR2 having been found to be highly expressed in NE cells of PCa, the mechanisms through which upregulation of IL-8/CXCR2 signaling promotes NED and malignant progression of prostate adenocarcinomas post-ADT are not clear." (PMID 34799554, 2021).
rectal cancer (2 papers, 2014 to 2019). A primary or metastatic malignant neoplasm that affects the rectum. "Another study on interleukin genes and associations with colon and rectal cancer risk and overall survival showed SNPs from genes within the IL-8 pathway (IL8, CXCR1 and CXCR2) to have significant association with both colon and rectal cancer risk." (PMID 31244280, 2019).
respiratory infections (2 papers, 2024 to 2025). "Patients with CXCR2 LOF variants often exhibit increased susceptibility to upper respiratory infections." (PMID 41451234, 2025).
sarcoma (2 papers, 2021 to 2023). A usually aggressive malignant neoplasm of the soft tissue or bone. "In sarcoma-bearing mice, sarcoma tissue induces expansion of MDSCs that express CXCR2." (PMID 34359674, 2021).
skin infection (2 papers, 2021 to 2025). An inflammatory process affecting the skin, caused by bacteria, viruses, parasites, or fungi. "More importantly, inhibiting the Cxcl1–Cxcr2 axis with a Cxcr2 inhibitor or anti-Cxcl1 blocking antibody rescued defects in host defence against S. aureus skin infection in the GSDMD−/− mice." (PMID 34011393, 2021).
small cell lung carcinoma (2 papers, 2004 to 2020). Small cell lung cancer (SCLC) is a highly aggressive malignant neoplasm, accounting for 10-15% of lung cancer cases, characterized byrapid growth, and early metastasis. "Further, CXCL6 acts as an autocrine growth factor in tumor cells itself, i.e., in small cell lung cancer cells expressing its cognate receptors (CXCR1 and CXCR2)." (PMID 31963450, 2020).
systemic sclerosis (2 papers, 2011 to 2019). A chronic disorder, possibly autoimmune, marked by excessive production of collagen which results in hardening and thickening of body tissues. "The CXCR2 gene variability has been associated with several disorders like systemic sclerosis and cryptogenic fibrosing alveolitis, with a strong linkage between the +785C, +1208T, and +1440G alleles." (PMID 30863202, 2019).
thrombosis (2 papers, 2022 to 2023). "CXCR2, PSGL1, and the myeloid integrin CD11b (αMβ2), but not L-selectin knockouts, exhibit partial protection against venous thrombosis." (PMID 37954596, 2023).